MYO5B (myosin VB)
Diseases named in the same sentence as MYO5B in open-access papers (continued):
Sharing a sentence is not in itself a finding about the gene and the disease.
cholestasis (continued). "One would expect that if abnormal localization of BSEP is part of the mechanism underlying MYO5B-associated cholestasis, BSEP IHC results and the MYO5B genetic variations might similarly be linked to their clinical and biochemical disease features." (PMID 41511375, 2026). "None of the MYO5B-associated cholestasis cases with a follow-up of >5 years (median 9.1 years) received a liver transplant." (PMID 41511375, 2026). "Notably, while comprehensive genetic screening excluded mutations in other cholestasis-associated genes (ABCB4, FXR, TJP2, MYO5B, and USP53), both cases carried the p.A1028A concurrently with p.V444A." (PMID 40776909, 2025). "Several noncanonical variants in MYO5B have been associated with low GGT cholestasis in recent years; meanwhile, some new potential pathogenic MYO5B noncanonical variants have also been clinically detected." (PMID 40225142, 2023). "Disease-associated MYO5B noncanonical variants were collected from the literature or newly identified low GGT cholestasis patients." (PMID 40225142, 2023). "This poses a challenge for clinical management and genetic counseling; for example, a definitive genetic diagnosis cannot be made for some patients with low GGT cholestasis, and biallelic MYO5B VUSs identified due to caution should be exercised in clinical diagnostics regarding VUSs." (PMID 40225142, 2023). "MYO5B mutations have been associated with microvillus inclusion body disease (MVID), which affects the targeting of the tubule membrane by BSEP and leads to impaired bile acid excretion, ultimately causing cholestasis." (PMID 37324459, 2023). "We do not know whether the UNC45A mutations reported in O2HE patients who did present with cholestasis will lead to a similar loss of myosin Vb expression and whether any myosin Vb remaining will function properly in the absence of UNC45A or may behave as a dysfunctional/mutant-like myosin Vb." (PMID 35421597, 2022). "Together, these results suggest that the mechanism via which MYO5B variants cause cholestasis may not reflect a loss-of-function of myosin Vb, but a gain-of-toxic function of the mutant myosin Vb protein on active RAB11A at the interface of the trans-Golgi network and ARE." (PMID 33557414, 2021). "Instead, MYO5B-PFIC and treatment of cholestasis symptoms was evident." (PMID 33924896, 2021). "A recent study shows that the MID mouse, having total body knock-out of MYO5B, is not suitable to model cholestasis." (PMID 33383947, 2020). "Hence, the presence or absence of abnormal BSEP IHC results in MYO5B-associated cholestasis did not have clinical significance, and the aberrant localization of BSEP clearly was not the primary or sole mechanism responsible for MYO5B-associated cholestasis." (PMID 41511375, 2026). "The etiology of cholestasis in MVID is not clear, but may be caused by the MYO5B mutations carried by the patient and/or may be a complication of the TPN." (PMID 34501384, 2021). "Notably, no homozygous MYO5B variants that lead to the loss of myosin Vb protein expression (e.g., nonsense, frameshift variants), or to the premature truncated myosin Vb proteins that lack the RAB11A binding sites, have been associated with isolated cholestasis." (PMID 33557414, 2021).
familial intrahepatic cholestasis (7 papers, 2019 to 2026). An instance of intrahepatic cholestasis that is caused by an inherited modification of the individual's genome. "Variants of the MYO5B gene, which encodes the molecular motor protein myosin-Vb, have gained prominence as a causative factor in familial intrahepatic cholestasis (FIC)." (PMID 41511375, 2026). "Biallelic MYO5B variants have been associated with familial intrahepatic cholestasis (FIC) with low serum gamma-glutamyltransferase (GGT)." (PMID 40225142, 2023). "MYO5B mutations are one of the rare causes of progressive familial intrahepatic cholestasis (PFIC) with normal/low gamma-glutamyl transferase (GGT)." (PMID 34900494, 2021). "Genes associated with familial intrahepatic cholestasis (FIC) include ATP8B1 (FIC1), ABCB11 (FIC2), ABCB4 (FIC3), TJP2 (FIC4), NR1H4 (FIC5) and MYO5B (FIC6)." (PMID 33557414, 2021).
gastric cancer (6 papers, 2016 to 2023). A primary or metastatic malignant neoplasm involving the stomach. "It is noteworthy that decreased MYO5B expression was observed in gastric cancer, whereas missense mutations of this motor protein were associated with rare neural tumors, pheochromocytoma and paraganglioma." (PMID 33670106, 2021). "Although the function of MYO5B in OV remains unclear, the extracted silent mutation may possibly decrease its protein levels, promoting the growth of OV, as in gastric cancer." (PMID 37165041, 2023). "They found that MYO5B was repressed in 78.6% and 17.1% of gastric cancer and normal gastric tissues (p < 0.001)." (PMID 35884482, 2022). "Functional studies revealed that MYO5B depletion markedly stimulates migration and Matrigel invasion of gastric cancer cells." (PMID 33670106, 2021). "Studies showed that MYO5B (myosin VB) may become an important biomarker for gastric cancer because the expression of MYO5B was downregulated in gastric cancer and the inactivation of MYO5B may contribute to tumorigenesis." (PMID 36846347, 2023). "The deletion of MYO5B may affect the integrity of the intestinal brush margin, leading to dedifferentiation and tumor progression in patients with gastric cancer." (PMID 32670437, 2020).
intrahepatic cholestasis (6 papers, 2020 to 2022). A cholestasis characterized by impairment of the bile flow caused by obstruction located in the liver. "Conceivably, detrimental effects of MYO5B variants on bile canalicular protein trafficking mechanistically underlie the intrahepatic cholestasis." (PMID 33557414, 2021). "MYO5B variants were identified in patients with intrahepatic cholestasis and low/normal GGT serum levels." (PMID 33557414, 2021). "Liver biopsies of patients with intrahepatic cholestasis and MYO5B variants revealed a reduced expression and partial mislocalization of ABCB11, and in some cases also of ABCC2 and ABCB4." (PMID 33557414, 2021). "Our patient had normal-low GGT intrahepatic cholestasis and minimal bowel symptoms that closely resemble classical PFIC but was identified to have MYO5B mutation which is classically associated with microvillus inclusion disease." (PMID 36705120, 2022). "Because UNC45A mutations have also been associated with intrahepatic cholestasis in some O2HE patients, we examined the effect of UNC45A depletion on myosin Vb expression in hepatocellular HepG2 cells, widely used model cell lines for the study of hepatocellular biology." (PMID 35421597, 2022). "This is also supported by patient data that show that in contrast to missense MYO5B mutations, bi-allelic mutations in the MYO5B gene that are predicted to result in the loss of myosin Vb expression have not been identified in patients with isolated intrahepatic cholestasis." (PMID 35421597, 2022). "Bi-allelic MYO5B gene variants, with the exclusion of bi-allelic variants that cause premature termination codons or the loss of the RAB11A-binding site at the carboxyl-terminus of the myosin Vb protein, can also cause isolated intrahepatic cholestasis with no or only mild intestinal symptoms." (PMID 35893420, 2022).
progressive familial intrahepatic cholestasis (6 papers, 2021 to 2023). Progressive familial intrahepatic cholestasis (PFIC) refers to a heterogeneous group of autosomal recessive disorders of childhood that disrupt bile formation and present with cholestasis of hepatocellular origin. "Interestingly, mutations in MYO5B have also been reported as causative for progressive familial intrahepatic cholestasis (PFIC), and the literature demonstrates a strong correlation between mutation characteristics and disease phenotype." (PMID 36422736, 2023). "Recently, missense mutations in myo5b were also associated with progressive familial intrahepatic cholestasis (MYO5B-PFIC)." (PMID 33924896, 2021).
Cholestatic liver disease (3 papers, 2021 to 2026). "Bi-allelic MYO5B mutations are also identified in a subset of patients with predominant early-onset cholestatic liver disease." (PMID 33525641, 2021). "Genetic analysis using next-generation sequencing included a panel of five genes involved in cholestatic liver diseases (ATP8B1, ABCB11, ABCB4, ABCC2 and MYO5B)." (PMID 41797682, 2026).
hepatoma (3 papers, 2014 to 2025). "Live cell imaging of WIF-B9 cells, a polarized hybrid of human fibroblasts and rat hepatoma, visualized the recycling process and its association with myosin Vb and rab 11a; however, taurocholate and cAMP were ineffective, possibly because hybrid WIF-B9 cells lack regulatory components." (PMID 24643070, 2014).
liver disease (3 papers, 2021 to 2023). "However, exact differentiation between TPN-associated liver disease and MYO5B-PFIC cannot be clearly made in every case." (PMID 33525641, 2021). "The loss of MYO5B motor function alone does not cause liver disease." (PMID 33525641, 2021).
paraganglioma (3 papers, 2020 to 2023). A benign or malignant neoplasm arising from paraganglia located along the sympathetic or parasympathetic nerves. "MYO5B expression was reported to be upregulated in pheochromocytoma and paraganglioma tissues, and MYO5B mutation (p.L587P, p.G1611S, and p.R1641C) was demonstrated to be responsible for cancer cell proliferation and migration." (PMID 35478939, 2022). "In addition, subcellular localization of MYO5B protein was altered from cytoplasmic to membranous in some metastatic tumors, and the strongest and most abnormal expression pattern was observed in a paraganglioma harboring a somatic MYO5B:p.G1611S mutation." (PMID 32511227, 2020).
schizophrenia (3 papers, 2019 to 2023). A major psychotic disorder characterized by abnormalities in the perception or expression of reality. "Other possible, neuronally relevant candidate genes in the fear-associated locus in CFA7 that lie outside the human 18p11 locus include a myocin gene MYO5B that has been linked to schizophrenia and bipolar disorder." (PMID 30655508, 2019). "MYO5B gene and GGCX gene show strong associations with schizophrenia." (PMID 37510227, 2023). "In addition, dysfunction of glutamatergic signaling in the brain may be involved in the pathophysiology of schizophrenia, and myosin Vb (MYO5B) contributes to glutamate receptor 1(GluR1) signaling, suggesting a link between glutamatergic signaling and schizophrenia." (PMID 35855328, 2022).
Arrhythmia (2 papers, 2015 to 2025). Any cardiac rhythm other than the normal sinus rhythm. "Moreover, calcium handling and contractile function genes (SLN, ACTC1, PLCD4, PLCZ), potential arrhythmia-related genes (MYO5B, KCNA5), and cytoskeleton and cellular organization-related genes (XIRP2, COL8A1, KCNA6) were among the most deregulated genes in rTOF ventricles." (PMID 26252659, 2015).
enteropathy (2 papers, 2021 to 2022). "In this study we tested the hypothesis that UNC45A and myosin Vb, the losses of which are associated with 2 rare diseases with shared enteropathy, are functionally linked." (PMID 35421597, 2022).
heart failure (2 papers, 2015 to 2025). Inability of the heart to pump blood at an adequate rate to meet tissue metabolic requirements. "At around 7 months of age, αMHC-Cretg/- mice display DCM-like symptoms, a finding that necessitates further elucidation, especially against the background of heart failure in aged MYO5b-KO mice." (PMID 39969162, 2025). "In MYO5b-KO mice, heart failure is already at an advanced stage at 6 months of age and ends fatally shortly after this point." (PMID 39969162, 2025). "With further ageing, all MYO5b-KO mice of both sexes developed heart failure by the age of 6 months and displayed a 100% mortality (earliest at 27 weeks of age, latest at 41 weeks of age)." (PMID 39969162, 2025). "Impairment in MYO5b expression and function promotes cardiac dysfunction, heart failure, and death." (PMID 39969162, 2025). "Nonetheless, heart failure in MYO5b-KO mice develops earlier and tends to be more severe." (PMID 39969162, 2025). "Finally, the broad effect of MYO5b in postnatal cardiomyocytes suggests that its down-regulation in terminally failing human hearts may have contributed to the progression of heart failure." (PMID 39969162, 2025). "Furthermore, the global reduction in MYO5B in terminally failing human hearts may contribute to the progression of heart failure, and MYO5b might therefore emerge as a novel therapeutic target." (PMID 39969162, 2025).
neuroblastoma (2 papers, 2020 to 2024). Neuroblastoma (NB) is the most common solid, extracranial childhood tumor. "Some potentially damaging germline variants in these two genes have been reported previously in different other cancer types including CNS tumors, neuroblastoma (MYO3A), and single cases of osteosarcomas and RMSs (MYO5B)." (PMID 39037077, 2024).
pancreatic cancer (2 papers, 2022). "Notably, MYO5B was also up-regulated in pancreatic cancer and associated with poor prognosis." (PMID 36522691, 2022). "To screen genes showing a more significant advantage in pancreatic cancer prognosis, we then selected MYO5B and PSCA to establish a prognostic prediction model by univariate and multivariate cox regression analysis." (PMID 36522691, 2022). "Notably, both MYO5B and VPS4B within the rearrangement region were upregulated in pancreatic cancer and associated with poor prognosis." (PMID 35570408, 2022). "We determined the genes that express differently in pancreatic cancer tissues compared with normal tissues and associate with survival (P < 0.05) as Hub genes, yielding a total of six Hub genes, including S100A14, KRT8, KRT19, MAL2, MYO5B, and PSCA." (PMID 36522691, 2022).
atrial fibrillation (1 paper, 2025). A disorder characterized by an electrocardiographic finding of a supraventricular arrhythmia characterized by the replacement of consistent P waves by rapid oscillations or fibrillatory waves that vary in size, shape and timing and are accompanied by an irregular ventricular response. "Holter analysis confirmed individual ECG abnormalities such as supraventricular extra-systoles, intermittent bundle branch blocks, alterations in the periods between QRS complexes, and atrial fibrillation in MYO5b-KO compared with WT mice." (PMID 39969162, 2025).
Atrophy (1 paper, 2014). Any weakening or degeneration, especially through lack of use. "Conversely, Rab11a is mislocalised in Rab8a knockout mice and in a microvillus atrophy patient, which has a mutation in the myosin Vb gene." (PMID 25527643, 2014). "Conversely, the localisation of Rab11a is altered in the intestinal epithelial cells of Rab8a knockout mice and in a microvillus atrophy patient, which has a mutation in the myosin Vb gene." (PMID 25527643, 2014).
breast carcinoma (1 paper, 2026). "Furthermore, although MYO5B has been implicated in vesicle trafficking and epithelial polarity in other tissues, its role in breast cancer biology has remained largely unexplored." (PMID 41596426, 2026). "Together, our results demonstrate that LRP5 in osteocytes inhibits effects on breast cancer cells primarily by activating the LIMA1/MYO5B signaling axis." (PMID 41596426, 2026). "Our work is, to our knowledge, the first to systematically investigate MYO5B as a critical mediator of osteocyte-derived signals in breast cancer, thereby expanding the functional repertoire of both MYO5B and osteocytic Wnt signaling in the context of bone metastasis." (PMID 41596426, 2026). "Co-immunoprecipitation and immunofluorescence co-localization analyses revealed a specific interaction and spatial co-localization between exogenous LIMA1 and MYO5B in breast cancer cells, demonstrating that MYO5B is required for LIMA1-mediated inhibition of tumor cell migration and invasion." (PMID 41596426, 2026). "In summary, this study revealed that LRP5 overexpression in bone cells significantly inhibited breast cancer cell proliferation, migration, and invasion, and regulated osteoclast differentiation and immune response by activating the LIMA1/MYO5B signaling axis." (PMID 41596426, 2026). "In mouse models of breast cancer and breast cancer bone metastasis, LRP5-overexpressing osteocyte-derived CM markedly reduced tumor burden and osteolytic lesions, whereas genetic knockdown of either LIMA1 or MYO5B abolished these protective effects." (PMID 41596426, 2026). "In vivo, systemic administration of LRP5-overexpressing osteocyte-derived conditioned medium reduced mammary tumor burden and mitigated osteolytic bone destruction in tibial metastasis, whereas genetic disruption of LIMA1 in osteocytes or MYO5B in tumor cells abrogated these protective effects." (PMID 41596426, 2026). "In syngeneic mouse models of mammary tumors and bone metastasis, systemic administration of LRP5-overexpressing osteocyte-derived CM reduced tumor burden and osteolytic bone destruction, whereas genetic knockdown of LIMA1 in osteocytes or MYO5B in tumor cells abrogated these protective effects." (PMID 41596426, 2026).
cardiomyopathies (1 paper, 2025). "Further studies are required to substantiate our findings by exploring whether rare and likely pathogenic MYO5B gene variants are associated with the post natal manifestation of cardiomyopathies." (PMID 39969162, 2025).
colorectal cancer (1 paper, 2020). A primary or metastatic malignant neoplasm that affects the colon or rectum. "By functional prediction software, all five missense mutations were predicted to have an impact on the protein function, and none of the PPGL mutations were overlapping with previous reported MYO5B mutation spectra in colorectal cancer or MVID." (PMID 32511227, 2020). "Additionally, MYO5B mutations and methylation-independent loss of MYO5B expression that matched disease progression was recently reported in colorectal cancer." (PMID 32511227, 2020). "For example, MYO5A expression is increased in a number of highly metastatic cancer cell lines and metastatic colorectal cancer tissues, and epigenetic downregulation of MYO5B has been reported to promote proliferation, invasion and migration in gastric cancer." (PMID 32511227, 2020). "Low protein levels of MYO5B has been shown to be associated with motility of gastric cells, and expression level and mutations in MYO5B has been reported as a powerful prognostic biomarker in colorectal cancer, which might help to stratifying patients for adjuvant therapy." (PMID 32511227, 2020).
diarrheal disease (1 paper, 2023). The condition of having at least three loose or liquid bowel movements each day. "Indeed, loss-of-function MYO5B mutations cause neonatal diarrheal disease in children with microvillus inclusion disease, likely due to defects in apical polarization and transporter protein localization." (PMID 37165041, 2023).
glioblastoma (1 paper, 2023). The most malignant astrocytic tumor (WHO grade IV). "Serum exosomes of glioblastoma patients exhibited high levels of miR-98-5p, and its exosome targets STEAP3 and MYO5B were identified." (PMID 37569824, 2023). "Exosomal miR-19b-3p was highly expressed in the serum of glioblastoma patients, and its exosome targets SDC1, VPS4B, and MYO5B were identified." (PMID 37569824, 2023).
hepatopathy (1 paper, 2021). "Here, we thoroughly characterized the ultrastructural and immuno-cytochemical phenotype of hepatocytes and duodenal enterocytes from a unique case of an adult MYO5B-PFIC patient who showed constant hepatopathy but only periodic enteric symptoms." (PMID 33924896, 2021).
Hyperbilirubinemia (1 paper, 2025). An increased amount of bilirubin in the blood. "This case highlights that genetic etiologies, particularly MYO5B-related disorders, should be considered in patients presenting with recurrent hyperbilirubinemia, pruritus, and hepatosplenomegaly after excluding common causes (viral, autoimmune, drug-induced, or tumor-related)." (PMID 41822262, 2025).